NOL10 (nucleolar protein 10)
Synonyms: FLJ14075; PQBP5
Tractability: Small molecule: a structure with a bound ligand is known. PROTAC: ubiquitination databases record sites on it; its protein half-life has been measured.
Gene: Protein-coding gene on chromosome 2 (10,562,295 to 10,690,415, reverse strand). Ensembl gene ENSG00000115761.
Subcellular location: Nucleus, nucleolus
Subcellular location (Human Protein Atlas): Nucleoli
Gene Ontology:
Molecular function: RNA binding
Biological process: maturation of SSU-rRNA from tricistronic rRNA transcript (SSU-rRNA, 5.8S rRNA, LSU-rRNA)
Cellular component: nucleolus; small-subunit processome; nucleus
Genetic constraint (gnomAD): Loss-of-function variants: 33 observed, 43.8 expected, observed/expected ratio (o/e) 0.75, 90% interval 0.57 to 1.01. The upper end of that interval is the gene's LOEUF score, 1.01, which puts it in group 4 of 6, group 1 being the genes least tolerant of losing a copy. Missense variants: 403 observed, 420.73 expected, observed/expected ratio (o/e) 0.96, 90% interval 0.88 to 1.04. Synonymous variants: 152 observed, 150.03 expected, observed/expected ratio (o/e) 1.01, 90% interval 0.89 to 1.16.
Homologues: Orthologues: macaque NOL10 (99% identical), dog NOL10 (97% identical), chimpanzee NOL10 (97% identical), rabbit NOL10 (96% identical), mouse Nol10 (95% identical), rat Nol10 (95% identical), pig NOL10 (95% identical), guinea pig NOL10 (92% identical), tropical clawed frog nol10 (81% identical), zebrafish nol10 (73% identical), Drosophila melanogaster l(2)34Fd (46% identical), Caenorhabditis elegans nol-10 (44% identical).
Diseases named in the same sentence as NOL10 in open-access papers:
NOL10 is named in the same sentence as 18 diseases in open-access papers, as found by Europe PMC text mining. Sharing a sentence is not in itself a finding about the gene and the disease. The quoted sentences say what the papers report.
lung carcinoma (4 papers, 2019 to 2022). "Then, we further verified the expression of m6A related enzymes and the role hub gene (NOL10) closely related to survival in lung cancer cell lines." (PMID 35035657, 2022). "We discovered that suppressing the expression of the hub gene NOL10 greatly slowed lung cancer cell growth and migration." (PMID 35035657, 2022). "And reducing hub gene NOL10 expression substantially inhibited lung cancer cell growth and migration." (PMID 35035657, 2022). "The expression of NOL10 in lung cancer (LC) cell lines (H596 and A549), normal lung epithelial cells (BEAS-2B), and LC was examined to further confirm the function of NOL10." (PMID 35035657, 2022). "circNOL10 downregulation in lung cancer cells was co‐regulated by Pre‐NOL10 methylation and the splicing factor ESRP1." (PMID 30693177, 2019). "We also previously revealed that circRNA circ NOL10 could function as a tumor suppressor in lung cancer." (PMID 32493389, 2020). "circNOL10 expression was thus reduced more significantly than NOL10 mRNA in lung cancer cells." (PMID 30693177, 2019). "Furthermore, Pre‐NOL10 methylation and the splicing factor epithelial splicing regulatory protein 1 (ESRP1) worked together to downregulate circNOL10 expression in lung cancer, associated with significant inhibition of lung cancer development." (PMID 30693177, 2019). "Previous studies have reported that circNOL10 is involved in cell proliferation and cell cycle progression of lung cancer through the methylation of splicing factor epithelial splicing regulatory protein 1 (ESRP1), but the role of NOL10 in HCC is implicit." (PMID 33102213, 2020). "Overall, these results suggested that the low circNOL10 expression levels relative to NOL10 mRNA in lung cancer cells may be a consequence of co‐regulation by ESRP1 and Pre‐NOL10 methylation." (PMID 30693177, 2019).
prostate carcinoma (3 papers, 2024 to 2025). A carcinoma that arises from epithelial cells of the prostate gland. "Enp2/NOL10 expression had a significant effect in prostate cancer prognosis and severity; NOL10 is frequently mutated in specific cancers (4% in endometrial cancers cf. BioPortal) and is a critical dependency in some acute myeloid leukemias." (PMID 41000809, 2025). "Through unbiased proteomics screening, we reveal that the risk allele A of rs4519489 exhibits enhanced binding to USF1, a novel oncogenic transcription factor (TF) implicated in prostate cancer progression and prognosis, resulting in elevated NOL10 expression." (PMID 38645058, 2024). "Clinical findings reveal a synergistic effect between rs4519489 genotype and NOL10 expression on prostate cancer prognosis and severity." (PMID 38645058, 2024). "Furthermore, we elucidate that NOL10 regulates cell cycle pathways, fostering prostate cancer progression." (PMID 38645058, 2024). "The concurrent expression of NOL10 and USF1 correlates with aggressive prostate cancer characteristics and poorer prognosis." (PMID 38645058, 2024).
breast carcinoma (1 paper, 2025). "This study suggested that CASC3 can regulate the expression of circ-NOL10 and govern the tumorigenesis and progression of breast cancer." (PMID 40978141, 2025). "Overexpression of circ-NOL10 inhibited cell proliferation, migration, and invasion and induced apoptosis in breast cancer." (PMID 40978141, 2025). "Inhibition of CASC3 suppressed the expression of circ-NOL10 in breast cancer." (PMID 40978141, 2025).
colon cancer (1 paper, 2023). "As compared to control group, the expression of circ-NOL10, circ-LDLRAD3, circ-RHOT1, and CEA level in CRC, colon cancer, and rectum cancer patients was significantly upregulated (P ˂ 0.001, 0.001, 0.002), while circ-SMARCA5 was insignificantly upregulated (P = 0.233, 0.264, 0.280 respectively)." (PMID 37587156, 2023).
hepatocellular carcinoma (1 paper, 2021). A malignant tumor that arises from hepatocytes. "A number of studies reported that SEMA3F, UCK2, NOL10, RAP2A, ZIC2 and SAC3D1 are associated with prognosis and tumour immune infiltration in hepatocellular carcinomas." (PMID 34760691, 2021). "HPA analysis of protein expression showed that PRDX6, GCLM, HTATIP2, NOL10, KIF18A, RAP2A and GDI2 were highly expressed in the hepatocellular carcinoma tissues compared with normal control tissues." (PMID 34760691, 2021).
leukemia (1 paper, 2020). A malignant (clonal) hematologic disorder, involving hematopoietic stem cells and characterized by the presence of primitive or atypical myeloid or lymphoid cells in the bone marrow and the blood. "AATF (also known as CHE1) participates in several cellular pathways, such as 40S ribosomal subunit synthesis in complex with NGDN (p = 0.0014, FC 0.95) and NOL10 (p = 0.0007, FC 0.85), and high AATF expression has been linked to variants of leukemia." (PMID 32192169, 2020).
polyp (1 paper, 2023). A usually exophytic mass attached to the underlying tissue by a broad base or a thin stalk. "For polyp patients, there were positive correlations between circ-RHOT1 and circ-NOL10, circ-LDLRAD3, CEA (P = 0.002, 0.039, 0.043 respectively)." (PMID 37587156, 2023).
tumor (6 papers, 2019 to 2023). "Here, we found that linear NOL10 expression was significantly down-regulated in BC tumor tissues compared with that in adjacent normal tissues." (PMID 33397365, 2021). "In our work, the positive correlations between biomarkers and immune cells suggested YWHAB, PPAT, and NOL10 likely related to tumor microenvironment, which affected the recruitment of infiltrating immune cells into the tumor microenvironment of HCC." (PMID 33102213, 2020). "Circ-SMARCA5 and circ-NOL10 may act as tumor suppressors, while circ-LDLRAD3 and circ-RHOT1 may be oncogenes." (PMID 37587156, 2023). "This suggested that low circNOL10 expression in tumor cells was unlikely to be due to mutation of the NOL10 gene." (PMID 30693177, 2019). "We further knocked down the expression of PPAT, YWHAB, and NOL10 in HCC cells and found that depletion of PPAT, YWHAB suppressed the tumor proliferation." (PMID 33102213, 2020).
cancer (5 papers, 2021 to 2025). A tumor composed of atypical neoplastic, often pleomorphic cells that invade other tissues. "The role of telomerase in cancer was reviewed recently.Telomerase is associated with a set of accessory proteins, including dyskerin and nucleolar protein 10 (NOP10)." (PMID 35565379, 2022). "This leads to the expression of genes associated with β-catenin activation, which supports cancer progression, while circ-NOL10 inhibits cancer development by promoting the expression of SCML1 by inhibiting transcription factor ubiquitination." (PMID 40002172, 2025). "This study provides new insights into the possible implication of circ-SMARCA5, circ-NOL10, circ-LDLRAD3, circ-RHOT1 in CRC progression, where they are expressed differentially in CRC patients as well as non-cancer patients (UC, polyp, and piles)." (PMID 37587156, 2023). "Circ-SMARCA5, circ-NOL10, circ-LDLRAD3, and circ-RHOT1 were differentially expressed in patients with CRC as well as in non-cancer patients." (PMID 37587156, 2023). "Due to the dynamic variation of the expressions of circ-SMARCA5, circ-NOL10, circ-LDLRAD3 and circ-RHOT in cancer, and non-cancer patients, these circRNAs might be prospective candidates for early diagnosis of CRC." (PMID 37587156, 2023).
neurodegenerative disease (2 papers, 2023 to 2024). A disorder of the central nervous system characterized by gradual and progressive loss of neural tissue and neurologic function. "Therefore, understanding the role of PQBP5/NOL10 in the morphology and function of the nucleolus in physiological and pathological conditions would lead to investigations of the role of the nucleolus in the pathophysiology of neurodegenerative diseases." (PMID 36599853, 2023). "Moreover, PQBP5/NOL10 is sequestered to the inclusion bodies of polyQ disease proteins, which is the common mechanism of the polyQ category of neurodegenerative diseases." (PMID 39103492, 2024).
neurological diseases (2 papers, 2022 to 2023). "To date, however, gene mutations in PQBP5/NOL10 have not been extensively analyzed in neurodegenerative or neurological diseases." (PMID 36599853, 2023).
NOL10 also shares sentences with these, for which no sentence is quoted: acute myeloid leukemia (1 paper); colorectal cancer (1); dementia (1); endometrial cancer (1); invasive breast carcinoma (1); liver fibrosis (1); rectum cancer (1).